TAS2R2 (taste 2 receptor member 2 (gene/pseudogene))
Description:
Bitter taste receptor that detects natural and synthetic bitter compounds.
Synonyms: T2R2; TAS2R2P; T2R02; PS9
Gene: Processed pseudogene on chromosome 7 (12,491,095 to 12,492,004, forward strand). Ensembl gene ENSG00000203523.
Subcellular location: Cell membrane
Diseases named in the same sentence as TAS2R2 in open-access papers:
TAS2R2 is named in the same sentence as 3 diseases in open-access papers, as found by Europe PMC text mining. Sharing a sentence is not in itself a finding about the gene and the disease.
TAS2R2 shares sentences with these, for which no sentence is quoted: tumor (2 papers); head and neck squamous cell carcinoma (1); infection (1).